NFIL3 (nuclear factor, interleukin 3 regulated)
Diseases named in the same sentence as NFIL3 in open-access papers (continued):
Sharing a sentence is not in itself a finding about the gene and the disease.
pancreatic cancer (2 papers, 2019 to 2024).
prostate carcinoma (2 papers, 2017 to 2026). A carcinoma that arises from epithelial cells of the prostate gland. "We also show that SKP2 overexpression in prostate cancer PC3 cells increases the protein levels of TWIST1 and the expression of EMT related genes, including FMOD, THY1, NFIL3 and IRF2, leading to a marked increase in migration and invasion." (PMID 41542047, 2026). "Moreover, 8 of these TFs (FOXJ2, GATA6, NFE2L1, NFIL3, PRRX2, TEF, EBF2 and ZBTB18) were found to be differentially expressed in this study making them not only candidate biomarkers of prostate cancer but also potential therapeutic targets." (PMID 28380430, 2017).
Sepsis (2 papers, 2024 to 2025). Sepsis is defined as life-threatening organ dysfunction caused by a dysregulated host response to infection. "Sepsis patients showed a large upregulation of the ferroptosis-associated gene ACSL4, as well as a considerable upregulation of NFIL3." (PMID 39097582, 2024). "What is noticeable is that the expression level of ACSL4, a key molecule in ferroptosis, was significantly and positively correlated with NFIL3 in sepsis patients." (PMID 39097582, 2024). "In this study, our analysis based on the GEO database found that NFIL3 expression was elevated in patients with sepsis and significantly positively correlated with ACSL4." (PMID 39097582, 2024). "In this study, we analyzed the GSE134347 dataset and found that the rhythm gene NFIL3 is highly expressed in sepsis patients, inducing ferroptosis in renal tubular cells through upregulation of ACSL4." (PMID 39097582, 2024). "Sepsis can lead to circadian dysregulation, and the rhythm gene NFIL3 has been reported to regulate lipid metabolism." (PMID 39097582, 2024). "In addition, analysis of the GEO database showed that NFIL3 was highly expressed in sepsis patients and was highly correlated with the key molecule of ferroptosis, ACSL4." (PMID 39097582, 2024). "Additionally, the rhythm gene nuclear factor, interleukin 3 regulated (NFIL3), which is highly expressed in sepsis patients and correlates with ACSL4, modulates ferroptosis and inflammation in SA-AKI by promoting ACSL4-dependent lipid peroxidation in renal tubular epithelial cells." (PMID 41250137, 2025). "To explore the mechanisms causing ferroptosis in SA-AKI, we first analyzed the GSE134347 dataset and found that the rhythm gene NFIL3, together with important contributor to ferroptosis ACSL4, was significantly highly expressed in sepsis patients compared to healthy controls." (PMID 39097582, 2024). "However, the role of the rhythm gene NFIL3 in ferroptosis during sepsis has not been reported yet." (PMID 39097582, 2024).
viral infection (2 papers, 2022 to 2025). "The high expression of NFIL3 has been well documented in T-cell activation and specific virus infection." (PMID 36439145, 2022).
amyotrophic lateral sclerosis (1 paper, 2020). Amyotrophic lateral sclerosis (ALS) is a neurodegenerative disease characterized by progressive muscular paralysis reflecting degeneration of motor neurons in the primary motor cortex, corticospinal tracts, brainstem and spinal cord. "Expression changes of ACTN1 were associated with AD in hippocampus, whereas NFIL3 was associated with neuroprotection in models of Amyotrophic Lateral Sclerosis." (PMID 32493431, 2020).
brain tumor (1 paper, 2016). "Similarly, SULT4A1, with lower expression in children brain tumor, is regulated positively by NFIL3 in normal samples while negatively by NFIL3 in NG group." (PMID 27586240, 2016).
depression (1 paper, 2010). "Two NFIL3 variants were modestly associated with depression and fatigue, with best evidence for rs1619450 (P = 0.017, OR = 0.59); there was a similar association for one CSNK1E variant, rs135745 (P = 0.015, OR = 1.34)." (PMID 20174623, 2010).
ductal carcinomas (1 paper, 2024). "On the other hand, NF was higher in normal tissue than tumor tissue, and the immunohistochemical analysis indicated NFIL3 protein expression was negative in normal breast tissue as well as in ductal carcinomas." (PMID 39765744, 2024). "IFNGR1 and NFIL3 protein expression levels were negative in normal breast tissue as well as in ductal carcinomas." (PMID 39765744, 2024).
E. coli infection (1 paper, 2023). "Therefore, we also investigated the transcriptional changes in interleukin-family genes and found that E. coli infection significantly increased the expressions of IL-1α, IL-11, NFIL-3, IL-16, and other cytokines." (PMID 36876070, 2023).
emphysema (1 paper, 2024). "Consequently, we selected mice exposed to tobacco for 12 weeks to evaluate the expression of Tim3 and NFIL3 in CD4+ T cells during the early stages of emphysema." (PMID 39555065, 2024).
eosinophilic disorders (1 paper, 2023). "Additionally, blocking the Pim-1/NFIL3 axis or selective elimination of GR-mediated TA restores apoptosis in IL-5-activated eosinophils suggesting NFIL3’s role in treating eosinophilic disorders associated with steroid resistance." (PMID 37664635, 2023).
fetal growth restriction (1 paper, 2018). A fetus that does not grow beyond the 10th percentile of conventionally accepted weight for gestational age. "However, both cell number and factor-secreting abilities are significantly reduced in Nfil3−/− (E4BP4-deficient) mice resulting in fetal growth restriction." (PMID 30319610, 2018).
hypotension (1 paper, 2018). "Instead, these results suggest that vascular dysfunction in the subset of aged Nfil3−/− mice with seemingly normal RVSP extends to the systemic circulation, causing systemic hypotension in these animals." (PMID 30234375, 2018).
ischemia (1 paper, 2024). A hypoperfusion of the BLOOD through an organ or tissue caused by a PATHOLOGIC CONSTRICTION or obstruction of its BLOOD VESSELS, or an absence of BLOOD CIRCULATION. "The tissues of cerebral ischemic scars were taken for IHC staining and Western blotting, and the expressions of FOS, DDIT3, DUSP1 and NFIL3 after ischemia were detected." (PMID 38384585, 2024).
liver failure (1 paper, 2015). A liver disease characterized by the liver losing or has lost all of its function. "Interestingly, Nfil3−/−, but not CD1d−/−, BM lost the ability to rescue Fah−/− mice from liver failure since Nfil3−/− BMT markedly decreased Fah−/− mouse survival and Fah+ BMDH generation after NTBC withdrawal." (PMID 26345133, 2015).
melanoma (1 paper, 2020). A malignant, usually aggressive tumor composed of atypical, neoplastic melanocytes. "The reason why NFIL3 differently expressed in the response of anti‐PD1 therapy in melanoma and renal cell carcinoma may be that NFIL3 expression is associated with infiltration of different immune cells in these two cancer types." (PMID 31927791, 2020).
metabolic dysfunction-associated steatotic liver disease (1 paper, 2024). Metabolic dysfunction-associated steatotic liver disease (MASLD, formerly known as nonalcoholic fatty liver disease or NAFLD) is a type of liver disease that is not caused by alcohol. "However, studies on the role of Nfil3 in metabolic dysfunction-associated steatotic liver disease (MASLD) are limited." (PMID 39048678, 2024). "This study investigates sex-specific effects in a gain-of-function model to evaluate Nfil3 function in relation to high-fat diet (HFD)-induced metabolic dysfunction-associated steatotic liver disease (MASLD) and gut microbiota (GM)-induced alterations in the bile acid (BA) profile." (PMID 39048678, 2024).
Parkinson disease (1 paper, 2024). A progressive degenerative disorder of the central nervous system characterized by loss of dopamine producing neurons in the substantia nigra and the presence of Lewy bodies in the substantia nigra and locus coeruleus. "Genes in the low-expression cohorts of DUSP1, FOS, and NFIL3 were mainly enriched in oxidative phosphorylation, as well as Parkinson's disease." (PMID 38384585, 2024).
peripheral nerve lesion (1 paper, 2015). "Here we tested whether genetic deletion or dominant-negative inhibition of NFIL3 could promote axon regeneration and functional recovery after peripheral nerve lesion in vivo." (PMID 25993115, 2015).
pulmonary hypertension (1 paper, 2018). Increased pressure within the pulmonary circulation due to lung or heart disorder. "We report the development of spontaneous pulmonary hypertension (PH) in both the Nfil3−/− and Ncr1-Gfp models of NK cell insufficiency, as exemplified by increased right ventricular systolic pressure (RVSP) and muscularization of the pulmonary arteries." (PMID 30234375, 2018).
renal cell carcinoma (1 paper, 2020). "However, in a human renal cell carcinoma dataset with anti‐PD‐1 treatment, we revealed that NFIL3 is highly expressed in the response group compared with the nonresponse group." (PMID 31927791, 2020).
retinal degeneration (1 paper, 2025). Degeneration of the retina. "As expected, these include clock genes such as Cry1 and Nfil3 (up) and Per3 and Nr1d2 (down) but also a few other genes, notably linked to retinal degeneration such as Myo7A61 that was substantially downregulated, or Loxl4 and Ppard that were highly upregulated." (PMID 40171795, 2025).
sarcoma (1 paper, 2019). A usually aggressive malignant neoplasm of the soft tissue or bone. "The expression level of NFIL3 in sarcoma tissue and normal bone tissues was compared through public database analysis, and NFIL3 was highly expressed in sarcoma tissues." (PMID 31886210, 2019). "Nuclear factor interleukin 3 (NFIL3) regulated was highly expressed in sarcoma tissues." (PMID 31886210, 2019).
type 2 diabetes mellitus (1 paper, 2022). A type of diabetes mellitus that is characterized by insulin resistance or desensitization and increased blood glucose levels. "All genes except ADIPOQ in Cluster 1 and Cluster 3 were upregulated in the NFIL3-high group and involved in IL-17 signaling pathways and the type II diabetes mellitus pathway." (PMID 36439145, 2022).
tumor (30 papers, 2011 to 2025). "For a comprehensive analysis across multiple cancer types, we employed pan-cancer data from UCSC, examining associations between NFIL3 expression and genomic heterogeneity, tumor mutational burden (TMB), microsatellite instability (MSI), tumor purity, and neoantigens." (PMID 38356719, 2024). "For example, tumour cells exhibited high activity of regulons regulated by TFs such as GATA2, NFIL3 and E2F1, which are associated with cell proliferation and survival." (PMID 40099956, 2025). "Transcription factors (TFs) associated with tumor metastasis and progression, such as SOX9, HMGA2, TP63, NFIL3, and IRF6, exhibited high transcriptional activity in the ITGA2hi‐PTC subcluster." (PMID 40985182, 2025). "When these tumor-bearing mice were treated with NK cells, the tumor size decreased to levels that were near those of wild-type Nfil3+/+." (PMID 39199674, 2024). "Our analysis of NFIL3 expression and tumor purity indicated significant positive correlations in HNSC and THYM." (PMID 38356719, 2024). "IRF6 expression levels were (p < 0.05) significantly higher in the tumor tissue, whereas NFIL3 was in normal adjacent tissues." (PMID 39765744, 2024). "NFIL3 is increased in many types of cancer by restricting FOXO chromatin access, and is associated with enhanced tumor cell survival and resistance to H2O2-mediated cell death." (PMID 35063803, 2022). "Consistently, the subcutaneous tumor formation assay also demonstrated that elevating NFIL3 protein promoted the growth of Hs578T cells, whereas decreasing NFIL3 protein inhibited the growth of Hs578T cells in vivo." (PMID 35180863, 2022). "Here the authors show that Smad3 inhibits NK cell differentiation and effector function by repressing NFIL3, and that genetic or pharmacological blockade of Smad3 expands tumour-suppressive NK cells and restricts tumour growth in mice." (PMID 28262747, 2017). "Both HLF and NFIL3 share the same DNA binding motif and are involved in regulation of circadian rhythms, cell death, and drug metabolism, with HLF acting as a transcriptional enhancer (oncogene) and NFIL3 as a transcriptional repressor (and sometimes tumor suppressor)." (PMID 40723261, 2025). "Therefore, we conducted an examination of the correlation between TMB, MSI, tumor purity, neoantigens, and NFIL3 expression." (PMID 38356719, 2024). "And, NFIL3 is related to tumor prognosis and immune regulation." (PMID 38356719, 2024). "Furthermore, anti-FGL1 mAb treatment was performed in Cd8–/– mice and Nfil3–/– mice challenged with MC38 tumor cells." (PMID 38973608, 2024). "NFIL3 was higher in the normal than in the tumor tissues (p = 4976518 × 10–2)." (PMID 39765744, 2024). "Studies using Nfil3−/− knockout mice demonstrated NK cells’ critical role in early cSCC tumorigenesis, as these mice developed significantly more papillomas and pre-cancerous protrusions, and had increased tumor growth." (PMID 39199674, 2024). "Although the ranking order may vary, the majority of the top-ranked TEff/EM regulons such as Rora, Fosl2, Creb3, Maf, Prdm1, Nfil3, and Nfkb1 were also identified as top-ranked regulons for active TRMs in the tumor and distant mammary mucosa." (PMID 33979626, 2021). "Among these upregulated genes, Dennd4a, Nfil3, Hspa1b, Chac1, Ddit4, Mex3b, Lysmd3, and Zbtb10 are mainly involved in oxidative stress and inflammation response, whereas Plcxd2, Dusp1, Cep85l, and Dusp8 are generally considered as tumor‐suppressor genes by inhibiting proliferation of cancer cells." (PMID 40231790, 2025). "Notably, heightened NFIL3 expression in cancer cell lines has been associated with a reduction in apoptosis occurrence and the inhibition of FOXO1 recruitment to specific genes linked to tumor suppression." (PMID 38356719, 2024).
tumor (continued). "A comprehensive study was conducted to investigate NFIL3 expression in human cancers and corresponding normal tissues, revealing that NFIL3 has lower expression levels in cancers compared to normal tissues, suggesting a potential tumor-suppressive role for NFIL3." (PMID 38356719, 2024). "However, conventional NK cells were dispensable for this innate lymphocyte-dependent anti-tumor responses because Nfil3-deficient mice, which have profoundly diminished NK cell compartment, did not exhibit accelerated tumor growth." (PMID 30298068, 2018). "Patient PD4252 had a LOH deletion of 9q in the primary tumour, where the remaining segments were incorporated into chromosome 1 with a LOH of 1p, forming an HSR with NFIL3 amplification (PD4252a)." (PMID 33927198, 2021). "Notably, NFIL3 expression demonstrated a robust correlation with several pivotal aspects, including prognosis, immune cell infiltration, immune checkpoint-related genes, TMB, MSI, tumor purity, and the presence of neoantigens." (PMID 38356719, 2024). "Because mice lacking Nfil3 (which do not have conventional NK cells) did not also show accelerated tumor growth in this model, the observation suggests that ILC1-like cells play an important role in mediating early tumor immunosurveillance." (PMID 31366131, 2019).
cancer (24 papers, 2014 to 2025). A tumor composed of atypical neoplastic, often pleomorphic cells that invade other tissues. "In conclusion, this comprehensive study highlights the complex and multifaceted role of NFIL3 in cancer biology, emphasizing its potential as both a diagnostic marker and a therapeutic target in various cancer types." (PMID 38356719, 2024). "The NF-κB signaling pathway, a well-known inflammatory pathway associated with cancer progression, was enriched in the top ten inflammatory signaling pathways regulated by NFIL3." (PMID 35180863, 2022). "Furthermore, CNV analysis of gene gain and loss in samples in various cancers were analyzed to examine NFIL3 mutation." (PMID 38356719, 2024). "Furthermore, a protein-protein interaction (PPI) network analysis identified several genes associated with NFIL3, some of which play crucial roles in cancer development." (PMID 38356719, 2024). "Notably, the study explored the relationship between NFIL3 gene expression and non-synonymous single nucleotide variations (SNVs) in multiple cancers, shedding light on potential mutation patterns that could inform cancer diagnosis and treatment." (PMID 38356719, 2024). "However, the mechanisms underlying the elevation of NFIL3 protein across cancers are unknown and deserve further study in the future." (PMID 35180863, 2022). "NFIL3 regulates diverse biological processes from circadian rhythm to cellular viability, as well as in immunological signal transduction, cancer, aging, and metabolism." (PMID 40723261, 2025). "Although there is little information on hematopoietic cancers, a recent pan-cancer study found that NFIL3 expression in cancerous tissues exhibited diminished levels when compared to normal tissue samples." (PMID 40723261, 2025). "Results also showed that NFIL3 positively correlated with dendritic infiltration in Luminal A and Luminal B cancer patients, indicating the importance of the immunological system in the defense of the body." (PMID 39765744, 2024). "Armed with this foundational knowledge, we embarked on a comprehensive pan-cancer analysis to explore the intricate relationship between NFIL3 expression and immune cell infiltration levels, drawing upon the TCGA Pan-Cancer datasets." (PMID 38356719, 2024). "The study also examined the correlation between NFIL3 expression and the prognosis of various cancer types." (PMID 38356719, 2024). "This work clearly demonstrates the normal tissue with high NFIL3 expression compared to their cancer tissue counterparts in most carcinomas." (PMID 38356719, 2024). "Limited research has been conducted to investigate the expression of NFIL3 across diverse cancer types." (PMID 38356719, 2024). "Subsequently, we conducted a comprehensive analysis of the prognostic significance of NFIL3 across various cancers in pan-cancer datasets." (PMID 38356719, 2024). "To assess NFIL3 expression in matched cancer and adjacent normal tissues, we conducted a comparative analysis of NFIL3 mRNA expression using the Kaplan-Meier Plotter database." (PMID 38356719, 2024). "In conclusion, NFIL3 is capable of acting as a prognostic biomarker and is closely related to the immune system, which points to its potential as a cancer immunotherapy." (PMID 38356719, 2024). "Lastly, there were significant differences in NFIL3 expression and prognosis between cancer and corresponding normal tissues in a substantial portion of cancer types." (PMID 38356719, 2024). "Our results showed that NFIL3 protein was significantly overexpressed in these detected cancer types compared with their normal tissues, suggesting an opposite result regarding the expression of NFIL3 at the mRNA and protein levels in pancancer." (PMID 35180863, 2022). "By investigating the expression change of NFIL3 mRNA across cancers, we found that NFIL3 was downregulated in most (13 out of 15) cancer types with significant NFIL3 alterations." (PMID 35180863, 2022).